AR (androgen receptor)
Diseases named in the same sentence as AR in open-access papers (continued):
Sharing a sentence is not in itself a finding about the gene and the disease.
prostate carcinoma (continued). "Persistent activation of the AR signaling program occurs both not only through molecular adaptations of the AR itself but also through a number of accessory oncogenic pathways promoting persistent AR activation, ultimately leading to progressive prostate cancer." (PMID 26566796, 2015). "Moreover, using prostate cancer cells with different AR and GR status, we demonstrated clearly that CpdA could exert its cytostatic effect via both receptors which correlated with CpdA's dual GR/AR ligand properties shown in our earlier studies." (PMID 26436695, 2015). "Furthermore, we detected AR-positive cells in the prostate cancer tumor." (PMID 26439622, 2015). "PABPC1 modulation of the AR is likely to have a significant impact on prostate cancer progression because the AR is a key factor regulating prostate cancer cell growth and factors capable of modulating AR function could have profound effects in modulating prostate cancer cell growth." (PMID 26176602, 2015). "In addition, miR-21 can regulate AR expression during the development of prostate cancer." (PMID 26252635, 2015). "Indeed, AR is a potent oncogene which plays a crucial role in the early development of prostate cancer, as well as in metastatic castration-resistant progression in prostate cancer." (PMID 25535400, 2014). "These initial observations prompted us to evaluate whether re-expression of ERα and the establishment of an alternate nuclear receptor-signalling axis (that is, ERα versus AR) in prostate cancer cells could represent an adaptive mechanism to evade AR-directed therapies." (PMID 25415230, 2014). "The functional importance of NAIP in immunogenic modulation was confirmed by demonstrating that a reduction in NAIP, whether mediated by treatment with enzalutamide or NAIP siRNA, in either AR+ or AR− prostate cancer cells, improved the cells' sensitivity to T cell-mediated killing." (PMID 25344864, 2014). "Interestingly, GDC-0980 treatment alone decreased AR levels and this effect could be enhanced further by the addition of CDX, suggesting that mTOR activity may contribute to elevated AR protein levels, similar to the signaling observed in prostate cancer." (PMID 25103565, 2014). "None of the prostate-cancer-associated mutants were able to promote AR polyubiquitination." (PMID 24508459, 2014). "Similarly, the results demonstrated that AR was also increased in prostate cancer tissue." (PMID 25535400, 2014). "Additionally, we showed that the antiandrogen enzalutamide enhances SPOP-mediated degradation of full-length AR, but not most AR variants in prostate cancer cells." (PMID 24508459, 2014). "Furthermore, the association between FOXA1 and ER in breast cancer and FOXA1 and androgen receptor (AR) in prostate cancer suggests that expression levels of FOXA1 may influence responsiveness to antihormonal treatment in hormone dependent cancers." (PMID 24849812, 2014). "However, corroboration between TGF-β and AR signaling in prostate cancer has also been reported." (PMID 25089270, 2014). "Lastly, the stapledpeptide used in this study, as well as other small molecules capable ofdisrupting the AR/FlnA interaction, might represent a promising approach tospecifically modulate AR functions in stromal tissue and rescue hormoneproliferative responsiveness in human prostate cancers." (PMID 25476896, 2014). "Studies have demonstrated that suppressing AR expression with RNA interference (RNAi) technology is an effective way to inhibit the growth of prostate cancer cells, indicating that this method may have the potential to overcome hurdles associated with AIPC treatment." (PMID 24798477, 2014). "Supporting this observation, nuclear localization of the truncated AR variants was not affected by HSP90 inhibition and AR variant:HSP90 complexes could not be detected in prostate cancer cells." (PMID 23674566, 2013).
prostate carcinoma (continued). "In addition, altered interaction of AR with pre-RC and replication machinery could circumvent the requirement for androgen and account for the continued critical role of AR in proliferation of castration-resistant prostate cancer cells." (PMID 23437213, 2013). "Consequently, combined with our results, higher transactivated AR with shorter CAG repeats might inhibit prostate cancer metastasis and predict a good prognosis on ADT." (PMID 23359804, 2013). "Notably, emodin may downregulate androgen receptor (AR) and lead to the inhibition of prostate cancer cell growth, suggesting that anthraquinone derivatives might modulate steroid receptor activity." (PMID 23864887, 2013). "The androgen receptor (AR) is a modular, ligand-inducible transcription factor that regulates the expression of genes that can drive the progression of this disease, and as a consequence, this receptor is a key therapeutic target for controlling prostate cancer." (PMID 23771019, 2013). "We suggest that AR plays an important role in telomere stability and replication of telomere DNA in prostate cancer cells, and that AR inactivation-mediated telomere dysfunction may contribute to genomic instability and progression of prostate cancer cells." (PMID 23363843, 2013). "Hence the inhibition of the PI3K/Akt pathway may result in the activation of the FOXO3a transcription factor, which may then induce the AR gene expression to protect cells from apoptosis of LNCaP prostate cancer cells." (PMID 23445528, 2013). "Finally, that the AR controls expression of its target genes such as c-Myc in a tissue specific manner suggests that the ideal agent for suppression of c-Myc expression in prostate cancer cells specifically would target AR, itself." (PMID 23704919, 2013). "On the contrary, in prostate cancer, as AR is still able to bind in the absence of FOXA1, a mutation in FOXA1 which inhibits its DNA binding capacity may not inhibit AR binding, but could instead alter its binding profile and transcriptional targets." (PMID 23420418, 2013). "Also, PTEN and AR expression has been shown to inversely correlate in prostate cancer." (PMID 24098661, 2013). "Abnormal AR activity is associated with various pathogeneses such as male infertility, androgen-insensitivity syndrome (AIS), polycystic ovarian syndrome (PCOS), spinal and bulbar muscular atrophy (SBMA), rheumatoid arthritis, hirsutism, baldness, acne, breast cancer, and prostate cancer (PCa)." (PMID 25866551, 2013). "Our data suggest that dual targeting of the AR and PKARIα is more effective in inhibiting LNCaP and LNCaPabl tumor growth than single treatment and may give a treatment benefit, especially in castration-resistant prostate cancers." (PMID 23736698, 2013). "Interestingly, AR was recently reported to activate glycolytic metabolism, suggesting that AR might have similar effects on metabolic control in prostate cancer to those exerted by Kras does in PDAC." (PMID 23724116, 2013). "AR can form a ternary membrane-associated signal complex with c-Src, estrogen receptor, and function cooperatively to activate Src kinase activity to stimulate prostate cancer cell growth in a non-transcription-dependent manner." (PMID 24130878, 2013). "Therefore, TMEFF2 upregulation in response to AR signaling may initially serve as a barrier for malignant progression of prostate cancer." (PMID 23405127, 2013). "In AR-negative cell lines ganetespib exposure resulted in the simultaneous disruption of signaling networks that have been implicated in the aberrant growth and survival of prostate cancer." (PMID 23152004, 2013). "Together, the data suggest that ganetespib may serve as an effective treatment strategy for prostate cancers driven by AR, truncated forms of the receptor that confer androgen independence, as well as castrate-resistant tumors no longer reliant on the receptor itself." (PMID 23152004, 2013).
prostate carcinoma (continued). "Thus, it remains to be determined whether this preemptive design of antiandrogens active on wild-type and prospective androgen receptor mutants will improve long-term survival in advanced castration-resistant prostate cancer." (PMID 23580166, 2013). "We propose there may be other unknown factor(s) mediating inhibition of NLS-C8 and NLS-C6 through AR interaction, while the fragment between 123 and 224 amino acids (area overlapping between N6 and C6) maybe essential for growth inhibition in prostate cancer cells." (PMID 23734213, 2013). "In addition, AR overexpression and AR gene amplification have been reported in prostate cancers." (PMID 22321971, 2012). "Therefore suppression of AR is one of the therapeutic strategies for prostate cancer patients." (PMID 23056607, 2012). "However, it was shown that the effect of EGF on AR transcription might be almost negligible compared to the induction by androgens in prostate cancer." (PMID 22922989, 2012). "Overexpression of NcoA4 has been shown to enhance AR transactivation induced by ligands other than active androgens, which may have negative implications for the success of hormonal therapies used in the treatment of prostate cancer." (PMID 22562579, 2012). "Activation of AMPK by B-DIM resulted in the down-regulation of AR and prostate-specific antigen (PSA) expression, and caused induction of cell apoptosis, suppression of mTOR pathway, and inhibition of prostasphere formation in human prostate cancer cells in vitro and in vivo." (PMID 23056607, 2012). "In addition, hypermethylation of the AR promoter may be involved in the progression of prostate cancer and downregulate expression of IGF1R." (PMID 23227263, 2012). "For example, knock-down of either Cyp40 or FKBP51 in prostate cancer cell lines decreased cellular proliferation; this was particularly evident in androgen-dependent cell lines where these co-chaperones promote the transcriptional activity of the androgen receptor." (PMID 22681779, 2012). "The ability of signaling cascades to influence AR function may play a significant role in the development and progression of prostate cancer where the increase in signal transduction activity has been associated with the acquisition of castration-resistant disease." (PMID 22761715, 2012). "Lately the many similarities between breast and prostate cancer have become widely appreciated, leading to important therapeutic implications, such as a phase II clinical trial that is currently underway to investigate the potential benefit of targeting AR in triple negative breast cancer." (PMID 22849360, 2012). "Interestingly, androgens (dihydrotestosterone, DHT) has been shown to induce EMT in LNCaP prostate cancer cells by activating Snail, and expression levels of androgen receptor (AR) correlated inversely with androgen-mediated EMT suggesting that low levels of AR was required for the EMT phenotype." (PMID 22857708, 2012). "Although previous studies have demonstrated that curcumin treatment modulates the levels and transcription activity of AR, the activation of PKD1 by curcumin and the inhibition of β-catenin activity might be another mechanism for the regulation of AR function and prostate cancer growth." (PMID 22523587, 2012). "Furthermore, during the progression of prostate cancer from androgen sensitive status to castrate resistant prostate cancer, the majority of prostate cancer cells still expresses AR, suggesting that AR signaling plays a critical role in the development and progression of prostate cancer." (PMID 22200028, 2011). "Thus, FUS is a novel co-activator of AR in prostate cancer cells." (PMID 21909421, 2011). "Importantly, cofactors have been suggested to play important roles in the development of androgen insensitive prostate cancer, by enhancing the ability of AR to maintain sufficient function in a low androgen environment for maintenance of cell growth and survival." (PMID 21935435, 2011).
prostate carcinoma (continued). "The opposite functions of the epithelial AR in different epithelial cells could then affect prostate cancer progression in TRAMP mice by favoring survival of differentiated tumor epithelium while suppressing proliferation of epithelial-basal intermediate cells." (PMID 21754978, 2011). "AR expression was assessed in these cells by quantitative RT-PCR (qPCR) and Western blot procedures and was compared to cultured primary human prostate stromal fibroblasts (PrSC) and to LNCaP prostate cancer cells that are models for AR action in prostate cancer." (PMID 21267466, 2011). "Moreover, in recent years, constitutively active AR splice variants lacking the ligand binding domain have been identified in AI prostate cancer cell lines and tissues, with the highest levels observed in late stage CRPC." (PMID 24212771, 2011). "In prostate cancer, Gamitrinib-mediated killing indistinguishably affected androgen-dependent and -independent cell types, which may contribute to its activity against TRAMP tumours, often characterised by loss of androgen receptor and androgen insensitivity." (PMID 21285984, 2011). "However this system might represent the hormone refractory stage of advanced prostate cancer in which AR is over-activated." (PMID 21747944, 2011). "However, several reports indicate that AR is still necessary for ADI prostate cancer growth." (PMID 21267413, 2011). "Therefore, FKBP5 might serve as a novel drug target to help disrupt AR-mediated signalling in prostate cancer." (PMID 21119664, 2011). "Interestingly, SPBP is highly expressed in the AR positive prostate cancer cell line LNCaP." (PMID 21935435, 2011). "Thus, BEZ 235 treatment in PTEN-deficient prostate cancer cells does not delineate which target is more potent for AR signal activation." (PMID 22110995, 2011). "Since 5α-reductase inhibitors change the testosterone-to-DHT ratio, and given the critical role of 5α-reductase in AR signaling, the different 5α-reductase expression levels may provide clues about response and resistance to 5α-reductase inhibitors in prostate cancer prevention." (PMID 22194926, 2011). "Moreover, as β-catenin has the ability to enhance androgen receptor (AR) function in prostate cancer, the obvious therapeutic goal to abrogate potential oncogenic AR/β-catenin interactions can be easily achieved through the chemopreventive properties of 4HPR also in hormone responsive cells." (PMID 20537156, 2010). "Therefore, further investigation of the regulatory mechanisms of AR in these different stages would be extremely important to understand the molecular basis of the switch between androgen-sensitive and insensitive during prostate cancer progression." (PMID 20946682, 2010). "Thus, patients with prostate cancer cells harboring such AR loss-of-function mutations will not benefit from aggressive hormone or anti-AR therapies even though they express AR protein." (PMID 20628607, 2010). "This suggests that the biochemical mechanism for loss of AR signaling-induced growth suppression is not identical, and not always coupled, to that associated with the gain of AR signaling-induced growth stimulation in prostate cancer cells." (PMID 20628607, 2010). "Thus, this subtype of AR-expressing prostate cancer cells remains castrate-sensitive." (PMID 20628607, 2010). "Thus, down-regulation of AR signaling is commonly therapeutic for prostate cancer." (PMID 20628607, 2010). "Thus, AR plays a vital role in both clinically localized and advanced prostate cancers." (PMID 19956729, 2009). "Moreover, since steroid-like compounds are expected to act as agonists of the androgen receptor, antagonists are given preference in terms of search for chemical compounds with potential therapeutic effects for human prostate cancer, which involves activation of the androgen receptor." (PMID 19503826, 2009).
prostate carcinoma (continued). "However, the involvement of the AS3 gene product into androgen receptor signaling and vitamin D receptor action in prostate cancer cells suggests that inactivation of AS3 may contribute to the development of androgen-independent prostate cancer." (PMID 19737411, 2009). "Therefore, the interaction between the AR and the entire Wnt signaling pathway needs to be further explored in order to characterize possible tumor refractory mechanisms in castration-resistant prostate cancer cells." (PMID 18218096, 2008). "Thus, the genes that are regulated in reduced DHT concentrations due to AR overexpression might be important in the progression of prostate cancer during the hormonal therapy." (PMID 18673534, 2008). "The direct association between prohibitin and nuclear hormone receptor complexes (ER and AR) has further revealed the functions of prohibitin in transcriptional regulation of diverse genes and suggests the potential importance of prohibitin in breast and prostate cancers." (PMID 21566741, 2008). "In addition, our immunohistochemical findings of reduced expression of AR in advanced prostate cancer specimens especially those that express C/EBPα is in agreement with recent demonstrations of altered AR expression especially in androgen-independent prostate cancer." (PMID 16774685, 2006). "RREB1 promotes prostate cancer by activating the transcription of SNHG4, which promotes DNA damage repair, the cell cycle, and resistance to the androgen-receptor antagonist enzalutamide." (PMID 41516419, 2026). "We also examined the correlation between the expression of AR signature genes (AR score) and IKBKE expression levels in TCGA prostate cancer patient samples." (PMID 41542764, 2026). "Together, these findings indicate that AR pathway inhibition in combination with IR treatment increased CD8+ T cells in PBMCs from patients with CRPC and T cell infiltration in prostate cancer patient specimens." (PMID 41542764, 2026). "Arm level gains, which are amongst the frequently altered genomic events in early prostate cancer, were equivalently distributed between AVPC and AR-positive (ARPC) tumors." (PMID 41542660, 2026). "Here, transcriptomic analysis of the LNCaP prostate cancer cell line shows a significant overlap in genes regulated by FUS and the androgen receptor." (PMID 41651986, 2026). "Elevated PRK1 levels and phosphorylated H3T11 correlate with prostate cancer aggressiveness, suggesting PRK1 inhibition as a potential therapeutic strategy for blocking AR-induced tumor proliferation." (PMID 40356745, 2025). "Again, obesity and insulin resistance has been reported in humans with low androgen/AR signaling activity, including hypogonadal men, ADT-treated prostate cancer and Kennedy’s disease patients." (PMID 40181329, 2025). "TBX21 expression was markedly elevated in prostate cancer cell lines compared with RWPE-1, with the highest levels observed in AR-positive cells." (PMID 41573646, 2025). "Decursin inhibits AR signaling indirectly by disrupting the Wnt/β-catenin signaling, downregulating cyclin D1 and c-myc, and suppressing androgen-independent PC3 prostate cancer cell proliferation." (PMID 41020902, 2025). "Our recent study shows that targeting PCNA/AR interaction with enzalutamide, PCNA-I1S, R9-AR-PIP, and/or T2AA induces cytotoxicity in both androgen-dependent prostate cancer cells and CRPC cells." (PMID 40391771, 2025). "ABCC5 facilitates prostate cancer advancement and enzalutamide resistance through the CDK1-mediated AR Ser81 phosphorylation pathway." (PMID 41363115, 2025). "Patient’s gender influences, indeed, the efficacy of immunotherapy in many solid tumors, and combination of AR antagonist, enzalutamide and anti-PDL1 mAb exerts a remarkably antitumor effect in mouse model of castrate-resistant prostate cancer." (PMID 39837817, 2025).